HGF (hepatocyte growth factor)
Diseases named in the same sentence as HGF in open-access papers (continued):
Sharing a sentence is not in itself a finding about the gene and the disease.
liver cancer (continued). "To validate our tumour findings, we looked at the effects of HGF treatment on β-catenin and Y654-β-catenin in two liver cancer cell lines, with and without CTNNB1 mutations." (PMID 21992464, 2011). "This suggests that the loss of c-Met/HGF signaling, accompanied by a loss of antioxidants such as superoxide dismutase (SOD1) and NRF2, and its down regulation led to enhancement of liver tumor growth in the c-myc model of liver cancer by promoting a more favorable environment for cancerous growth." (PMID 40149719, 2025). "Furthermore hepatocyte growth factor (HGF) could induce transcription of Snail1 by activating MAPK signaling pathway in liver cancer." (PMID 34917071, 2021). "By secreting vital cytokines and chemokines like HGF, TGF-β, PDGF, IL-6, and Wnt ligands that can directly affect the tumor cells, HSC activation can also directly impact the formation of liver cancer." (PMID 37790613, 2023). "The role of C3G/RAPGEF1, required for the proper function of HGF/MET signaling in HCC and HPCs, is highlighted, due to its ability to promote HCC growth and, regulate HPC fate and platelet-mediated actions on liver cancer." (PMID 38138981, 2023). "For instance, hepatocyte growth factor (HGF) and its receptor tyrosine kinase MET were first discovered in the 1980s due to their over-activation in liver cancers." (PMID 35912218, 2022). "HGF and its receptor MET play a key role in the occurrence and metastasis of liver cancer, and lactate can regulate the expression of HGF." (PMID 36686771, 2022). "The HGF/MET signaling controls autophagy and metabolism to regulate chemoresistance of liver cancer." (PMID 34120890, 2021). "Dysregulation of EGF, HGF, and IGF-1 plays a crucial role in the development of hepatic cancer and metastases." (PMID 34572344, 2021). "Specifically, HGF stimulates, whereas MET depletion or inhibition blocks, liver cancer immunogenicity." (PMID 32764535, 2020). "Hepatocyte growth factor (HGF) stimulates MMP-3 to initiate and maintain the EMT of HCC, favoring the invasion of ECM by liver cancer cells." (PMID 31886121, 2019). "Many studies on cantilever-based biochemical detection have been reported, and high sensitivity and low detection limits for protein detection such as early liver cancer markers alpha fetoprotein (AFP) and hepatocyte growth factor (HGF) have been achieved." (PMID 31362399, 2019). "There are several etiological factors and potent stimulators involved in liver cancer progression, such as hepatitis B virus (HBV), transforming growth factor-β-1 (TGF-β-1), and hepatocyte growth factor (HGF)." (PMID 26556861, 2015). "In the classic model, once liver cancer is generated, HSC activation in the peritumoral tissue contributes to HCC progression through the secretion of growth factors, cytokines and chemokines such as VEGF, HGF, TGF-β1, PDGF, IL-6 and CX3CL1." (PMID 38138981, 2023). "In liver cancer, EGFR activates hepatocyte growth factor (HGF) expression by repressing miR-26a/b expression, and the upregulation of paracrine HGF, which binds to the c-MET receptor of migrated cancer cells, promotes the proliferation of metastatic cancer cells." (PMID 33909822, 2021). "Further, we confirmed that IL-6 and HGF secreted by H-CAFs but not by the liver cancer cells were crucial to EMT of HCC cells." (PMID 32792856, 2020). "Thus, human liver cancer organoids have also been successfully derived from tumor needle biopsy samples by employing the hepatocyte growth factor (HGF) in the standard R-spondin culture method without Noggin." (PMID 33578886, 2021). "Plasma HGF was significantly associated with presence of cirrhosis (p = 0.0027) and with Model for End-stage Liver Disease (MELD) score (p < 0.0001), but not with OS in surgical liver cancer patients." (PMID 30374460, 2018).
liver cancer (continued). "The miR-122 is significantly downregulated in liver cancers and inhibits HCC intrahepatic metastasis by regulation of a disintegrin and metalloprotease family protein ADAM10 and ADAM17.61, 62 The hepatocyte growth factor (HGF) c-Met signaling cascade may involve in HCC metastasis." (PMID 29264318, 2014). "MiR-101 could also inhibit the proliferation of liver cancer cells by targeting zinc finger protein 217 (ZNF217), mitogen-activated protein kinases (MAPK)/extracellular signal-regulated kinase (ERK) signaling pathways, and hepatocyte growth factor (HGF)/c-MET axis." (PMID 36497343, 2022).
non-small cell lung carcinoma (57 papers, 1996 to 2025). A group of at least three distinct histological types of lung cancer, including non-small cell squamous cell carcinoma, adenocarcinoma, and large cell carcinoma. "As a result, hepatocyte growth factor/cellular–mesenchymal to epithelial transition factor (HGF/c-MET) inhibitors have emerged as a potential treatment for non-small cell lung cancer." (PMID 39204153, 2024). "Src phosphorylated on Y90 was found in MEFs transformed by oncogenic Src or in non-small cell lung carcinoma cells stimulated with HGF." (PMID 37428018, 2023). "Higher serum levels of IL-22 and HGF were observed in patients with non-small cell lung cancer (NSCLC) than in healthy subjects." (PMID 35719915, 2022). "(iii) The clinical trials in non-small cell lung cancer have utilised HGF or c-Met inhibition exclusively to inhibit this pathway (generally in combination with an epidermal growth factor receptor inhibitor)." (PMID 34199452, 2021). "Another study suggested that CAFs produce HGF in an NF-κB-dependent manner and HGF activates Met-dependent signaling in non-small cell lung cancer." (PMID 30927928, 2019). "In non-small cell lung cancer, miR-206 decreased hepatocyte growth factor (HGF)-induced cell EMT and angiogenesis by targetting c-MET/PI3K/AKT/mTOR pathway." (PMID 30135139, 2018). "Similarly, in murine models of human non-small cell lung cancer, treatment with vandetanib and cediranib initially led to tumor regression followed by resistance to therapy and progression that was associated with upregulation of both HGF and its receptor, c-MET." (PMID 29996818, 2018). "H1299 non-small cell lung cancer cells grow in tight colonies which scatter rapidly following addition of HGF." (PMID 28294115, 2017). "Aberrant activation of c-MET/HGF signalling leads to increased tumour proliferation, invasiveness and angiogenesis, resulting in poor prognosis in various human cancers, including non-small-cell lung cancer (NSCLC) and gastric cancer." (PMID 28315949, 2017). "Noteworthy, sensitivity to gefitinib could be restored in an EGFR-mutated non-small cell lung carcinoma (NSCLC) cell line by the inhibition of the HGF/c-Met axis." (PMID 26729094, 2015). "A number of inhibitors targeting the HGF/Met pathway are currently under development for the treatment non-small-cell lung cancer (NSCLC) and other solid tumors." (PMID 25946048, 2015). "It has been known that hepatocyte growth factor (HGF) induces gefitinib resistance in non-small cell lung cancer (NSCLC) cells." (PMID 24034993, 2013). "Immunohistochemical analyses of the effects of hepatocyte growth factor (HGF) and c-Met expression on tumour growth and angiogenesis were performed on 88 patients with non-small-cell lung cancers (NSCLCs)." (PMID 15083185, 2004). "We have studied the mitogenic, motogenic and morphogenic effects of hepatocyte growth factor (HGF), also known as scatter factor (SF), on 15 non-small-cell lung carcinoma (NSCLC) cell lines that have had their ras genotype determined." (PMID 9649128, 1998). "Studies also reported that miR-200a plays an active tumor-suppressing role in non-small cell lung cancer, and could also inhibit gefitinib resistance and enhance the radio-sensitivity by deactivating the HGF/c-Met pathway." (PMID 32083078, 2020). "Elevated HGF expression and c-MET amplification have been linked with acquired resistance to epidermal growth factor receptor tyrosine kinase inhibitors (EGFR TKIs) in patients with non-small cell lung cancer (NSCLC)." (PMID 27422720, 2016). "Finally, the bispecific antibody potently inhibits tumor growth in a non-small cell lung cancer xenograft model bearing a strong autocrine HGF-loop." (PMID 23812422, 2013). "The two molecules, c-MET and HGF have an increased expression in various cancers such as non-small cell lung carcinoma (NSCLC), gastric, ovarian, pancreatic, thyroid, breast, head and neck, colon, and kidney carcinomas." (PMID 35626056, 2022).
non-small cell lung carcinoma (continued). "However, the clinical value of serum HGF (sHGF) in patients with advanced non-small cell lung cancer (NSCLC), especially those receiving cytotoxic chemotherapy, remains unknown." (PMID 29069748, 2017). "Inhibition of hepatocyte growth factor (HGF)-mediated signaling prevents aberrant vascular morphology and ameliorates VEGFR inhibitor resistance in non-small cell lung cancer." (PMID 36901858, 2023). "SU11274 inhibits cell viability in c-Met-expressing non-small cell lung cancer (NSCLC) cells with IC50 values of 0.8–4.4 μM, and abrogates HGF-induced phosphorylation of c-Met and its downstream signaling." (PMID 29455657, 2018). "Hepatocyte growth factor (HGF) and phorbol 12,13-dibutyrate (PDBu) can induce CTTN expression, motility, and invasion ability, as well as invadopodia formation in non-small cell lung cancer (NSCLC)." (PMID 29986736, 2018). "Overexpression of both HGF and/or its receptor c-MET have been reported in non-small cell lung cancer (NSCLC) cell lines and patients." (PMID 29069748, 2017). "For example, miR-206 inhibits HGF-induced EMT process and angiogenesis via PI3K/Akt/mTOR signaling pathway in non-small-cell lung cancer.TGF-β2 induces the EMT process via activation of PI3K/Akt/mTOR signaling pathway in cultured human lens epithelial cells." (PMID 28864782, 2017). "In this study, we examined the impact of CAF or HGF on the Met/PI3K/AKT phosphorylation, GRP78 expression and paclitaxel-induced apoptosis in human non-small cell lung cancer A549 cells cultured in the 3D matrix." (PMID 26115510, 2015). "When both HGF and AREG are present in vitro, downstream signaling to MAPK and Akt in non-small cell lung cancer (NSCLC) cells can only be completely inhibited by targeting both pathways." (PMID 21390244, 2010). "in non-small cell lung cancer demonstrated that CAFs promote ANXA2 expression and phosphorylation via secretion of hepatocyte growth factor (HGF) and insulin-like growth factor 1 (IGF-1), activating c-MET and IGF-1R receptors, thereby enhancing the epithelial–mesenchymal transition (EMT) process." (PMID 40837013, 2025). "In hepatocyte growth factor (HGF)-stimulated non-small-cell lung cancer (NSCLC) cells, ERK2 silencing, but not ERK1, significantly impairs tumor cell motility." (PMID 40723336, 2025). "Similarly, functional heterogeneity was also reported in non-small-cell lung cancer, where three CAF subpopulations that differentially expressed hepatocyte growth factor (HGF) and fibroblast growth factor 7 (FGF7), were reported." (PMID 35892828, 2022).
lung fibrosis (56 papers, 2006 to 2026). "In this study, we confirmed that treatment with UCMSCs or HGF-UCMSCs could alleviate pulmonary fibrosis caused by bleomycin in mice." (PMID 36726784, 2022). "Bleomycin-induced pulmonary fibrosis in mice revealed that MSC-derived hepatocyte growth factor (HGF) suppressed TGF-β1-driven collagen deposition and myofibroblast activation, improving lung compliance." (PMID 40809065, 2025). "This anti-pulmonary fibrosis of intratracheal iPSCs-conditioned medium was subsequently reported to be partially mediated by hepatocyte growth factor (HGF), accompanied by reduction of the collagen deposition, TGFβ1, and α-SMA expression in rat lungs." (PMID 38886859, 2024). "Administration of HGF protein or ectopic expression of HGF induced normal tissue repair and prevented fibrotic remodeling in animal models of pulmonary fibrosis." (PMID 39866352, 2024). "In the present study, we evaluated the therapeutic outcome of HGF-UCMSCs in rats with pulmonary fibrosis induced by bleomycin." (PMID 36726784, 2022). "It has been demonstrated that HGF functions as a protective protein in pulmonary fibrosis through binding its receptor, c-met, which is expressed by many types of cells (e.g., epithelial cells, fibroblasts)." (PMID 36726784, 2022). "Some researchers have used MSCs genetically modified with factors such as CXCR4, basic fibrosis growth factor (bFGF), and HGF to mitigate the effects of acute and chronic lung injuries and pulmonary fibrosis." (PMID 33747095, 2021). "DPSCs-HGF have a robust ability to modulate inflammatory and fibrotic cytokines and inhibit lung inflammatory and pulmonary fibrosis." (PMID 33747095, 2021). "Then, additional fibrotic factors, such as collagen I, TIMP, and MMP-9, were analyzed to evaluate the inhibitory effect of DPSCs-HGF on lung fibrosis progression." (PMID 33747095, 2021). "In a similar study, reduced HGF expression in MSCs impaired their ability to protect against lung fibrosis in vivo, in a mouse model of Bleomycin-induced pulmonary fibrosis." (PMID 33580031, 2020). "Administration of HGF to bleomycin-induced pulmonary fibrosis in mice increased lung MMP activities and enhanced myofibroblast apoptosis." (PMID 33149192, 2020). "The mechanisms by which LMWH suppressed lung fibrosis were suggested to be suppression of fibrosis formation by HGF and extracellular matrix (ECM)-degrading enzymes." (PMID 33149192, 2020). "HGF is involved in embryogenesis, angiogenesis, and tissue regeneration, and HGF administration has been used to prevent or resolve liver, kidney and lung fibrosis in animal models." (PMID 31137626, 2019). "Some secreted mediators involved in their therapeutic effect including IL1-RA, hepatocyte growth factor (HGF) have been identified in murine models of lung fibrosis." (PMID 30619298, 2018). "Taken together, our data further demonstrated that HGF upregulation played an important role in mediating the therapeutic effects of transplanted OSM‐preconditioned MSCs in alleviating lung fibrosis in the mice." (PMID 28297588, 2017). "HGF exerts therapeutic action in a variety of injury and disease models, including acute and chronic renal failure, pulmonary fibrosis, cardiac ischemia, and fibrosis." (PMID 28387740, 2017). "We conclude that the D1398G variant of MET is associated with compromised phosphorylation and impaired HGF signaling in lung fibroblasts and AEC, two cell types implicated in the pathogenesis of pulmonary fibrosis associated with scleroderma." (PMID 27584154, 2016). "MET is also expressed by myofibroblasts, where HGF exerts an anti-fibrotic effect and preserves organ function in bleomycin-induced lung fibrosis models." (PMID 27584154, 2016). "In particular, we showed that targeted, electroporation-mediated expression of HGF specifically in alveolar type II epithelial cells results in a reduction of lung fibrosis in the bleomycin-induced lung fibrosis model." (PMID 25384638, 2014).
lung fibrosis (continued). "We show in this study that the secretome of iPSCs induces alveolar epithelial repair in vitro and reduces lung fibrosis in vivo, in part by a HGF-dependent mechanism." (PMID 25384638, 2014). "Since HGF-transfected BMSC reduce bleomycin induced lung fibrosis in the bleomycin lung injury and fibrosis model, we assume that HGF-expressing, bone-marrow derived stem cells in UIP have antifibrotic properties." (PMID 23840329, 2013). "In vivo experiments showed that HGF-expressing BMSC attenuated bleomycin induced pulmonary fibrosis in the rat, indicating a beneficial role of bone marrow derived, HGF secreting stem cells in lung fibrosis." (PMID 23840329, 2013). "The inhibitor of TGF-β/Smad signal pathways may be a strategy for prophylactic treatment of pulmonary fibrosis progression, and its cooperation with the expression of hepatocyte growth factor in pulmonary capillaries reduced silicosis fibrosis." (PMID 38603722, 2024). "HGF mediated by MSCs had protective effects on an in vivo pulmonary fibrosis model." (PMID 39768142, 2024). "However, the application of HGF-UCMSCs in the treatment of bleomycin-induced pulmonary fibrosis has rarely been reported." (PMID 36726784, 2022). "Furthermore, secretions of anti-fibrotic factors such as HGF and prostaglandin E2 (PGE2), which have been associated with ameliorating lung fibrosis, were elevated compared with those of the control group." (PMID 35741711, 2022). "It is well recognized that administration of hypoxia-preconditioned MSCs could attenuate bleomycin-induced pulmonary fibrosis and these effects were mainly due to MSCs-derived HGF." (PMID 35012648, 2022). "HGF also plays a controversial role in fibrosis, since some studies show its inhibitory effect on lung fibrosis by antagonizing TGFβ but other studies report HGF up-regulation in SSc skin and increased HGF production in SSc fibroblasts compared with normal fibroblasts." (PMID 36014018, 2022). "In addition, HGF promotes active regeneration of lung tissue and prevents its fibrosis; in turn, G-CSF also prevents lung fibrosis by inducing directed migration of bone marrow cells into the damaged area of lung tissue." (PMID 36290634, 2022). "C-MET gene, encoding for the tyrosine kinases receptor for hepatocyte growth factor (HGF), could collaborate in maintaining tissue plasticity and the regenerative potential that characterizes pulmonary fibrosis." (PMID 35392967, 2022). "To explore the possible mechanism of HGF-UCMSCs in treating pulmonary fibrosis, we detected the cytokines that may participate in the process." (PMID 36726784, 2022). "In vivo studies have reported that HGF induces apoptosis and prevents accumulation of myofibroblasts in experimental lung fibrosis, while in vitro studies have shown that HGF intercepts with SMAD signaling activity involved in the regulation of TGF-β and inhibits epithelial-mesenchymal transitions." (PMID 33419174, 2021). "DPSCs-HGF ameliorated pulmonitis and pulmonary fibrosis in PQ mice, effectively improving the survival rate, which might be mediated by paracrine mechanisms." (PMID 33747095, 2021). "This is the first report showing that DPSCs are a suitable cell source and that the transplantation of DPSCs-HGF may be an effective approach to prevent the progression of lung inflammation and pulmonary fibrosis." (PMID 33747095, 2021). "Of note, HGF is a pleiotropic cytokine with anti-inflammatory properties playing a fundamental role in lung tissue repair, and CXCL13, a pro-inflammatory chemokine associated with pulmonary fibrosis and regulating the maturation of B cell response." (PMID 34373466, 2021). "While EC-derived HGF prevents acute injury-induced mouse lung fibrosis by acting on perivascular fibroblasts in the niche, chronic lung injury stimulates ECs to provoke fibroblasts and induces lung fibrosis." (PMID 31781555, 2019).